OR8B4 (olfactory receptor family 8 subfamily B member 4)
Description:
Odorant receptor.
Synonyms: OR8B4P; OR11-315
Tractability: Antibody: UniProt places it where antibodies can reach, with medium confidence; UniProt predicts a signal peptide or a membrane-spanning region; its Gene Ontology location is reachable by antibodies, with medium confidence.
Gene: Protein-coding gene on chromosome 11 (124,423,942 to 124,424,871, reverse strand). Ensembl gene ENSG00000280090.
Subcellular location: Cell membrane
Pathways (Reactome):
Sensory Perception: Expression and translocation of olfactory receptors
Gene Ontology:
Molecular function: olfactory receptor activity; G protein-coupled receptor activity
Biological process: G protein-coupled receptor signaling pathway; sensory perception of smell; detection of chemical stimulus involved in sensory perception of smell
Cellular component: plasma membrane; membrane
Genetic constraint (gnomAD): Loss-of-function variants: 3 observed, 2.33 expected, observed/expected ratio (o/e) 1.29, 90% interval 0.52 to 1.91. That is too few expected variants to judge how well the gene tolerates losing a copy. Missense variants: 360 observed, 388.54 expected, observed/expected ratio (o/e) 0.93, 90% interval 0.85 to 1.01. Synonymous variants: 139 observed, 152.51 expected, observed/expected ratio (o/e) 0.91, 90% interval 0.79 to 1.05.
Homologues: Orthologues: macaque OR8B4 (93% identical), chimpanzee OR8B4 (86% identical), mouse Or8b4 (86% identical), pig OR8B4 (85% identical), rat Or8b4 (84% identical), rabbit OR8B4 (84% identical). Paralogues in human: OR8B3 (68% identical), OR8B2 (68% identical), OR8B8 (67% identical), OR8B12 (64% identical), OR8G1 (58% identical), OR8G5 (58% identical), OR8G3 (58% identical), OR8A1 (57% identical), OR8D1 (57% identical), OR8D2 (56% identical), OR8D4 (56% identical), OR8G2P (56% identical), and 84 more.